ARNT (aryl hydrocarbon receptor nuclear translocator)
Diseases named in the same sentence as ARNT in open-access papers (continued):
Sharing a sentence is not in itself a finding about the gene and the disease.
acute myeloid leukemia (2 papers, 2017 to 2025). Acute myeloid leukemia (AML) is a group of neoplasms arising from precursor cells committed to the myeloid cell-line differentiation. "Additional regulators include aryl hydrocarbon receptor nuclear translocator in acute myeloid leukemia (AML), CREB-1, activating transcription factor 1 (ATF-1), and HIF-1α." (PMID 40722952, 2025).
breast tumors (2 papers, 2018 to 2023). "The strong correlation between high AHR and ARNT levels in both ERα-negative and ERα-positive tumors also suggests that the heterodimer, AHR-ARNT (AHR nuclear translocator), could be active in breast tumors." (PMID 29320557, 2018).
cardiomyopathy (2 papers, 2020 to 2023). A disease of the heart muscle or myocardium proper. "Interestingly, during diabetes, ARNT expression is also reduced and cardiac deletion of Arnt in mice causes an increase in lipid accumulation and consequent cardiomyopathy." (PMID 32816039, 2020). "ARNT plays a significant role in preventing the development of cardiomyopathy and subsequent heart failure." (PMID 37508425, 2023). "ARNT itself plays an essential role in the development of the cardiovascular system, regulating angiogenesis, limiting inflammatory cytokine production, and protecting against cardiomyopathy." (PMID 37508425, 2023).
clear cell renal cell carcinoma (2 papers, 2021 to 2025). "ARNT was recently found upregulated in clear cell renal cell carcinoma: its expression was responsible for cell migration/invasion and, coherently with our data also for the regulation of glycolytic enzymes like PFKFB3, (6−phosphofructo−2−kinase/fructose−2,6−bisphosphatase 3) and HK2 (hexokinase-2)." (PMID 35251951, 2021).
colorectal tumor (2 papers, 2021 to 2023). "ARNT deletion significantly promoted the occurrence and number of colorectal tumors, although it did not significantly change the weight of mice." (PMID 36859266, 2023).
ischemia (2 papers, 2021 to 2023). A hypoperfusion of the BLOOD through an organ or tissue caused by a PATHOLOGIC CONSTRICTION or obstruction of its BLOOD VESSELS, or an absence of BLOOD CIRCULATION. "Active Hif is a heterodimer, composed of an α subunit (Hif1α or Hif2α) and a β subunit (Hif1β, also called ARNT), and can bind hypoxia-responsive element (HRE), which is a very important mechanism in intestinal iron absorption and under other conditions, such as cancer and ischemia." (PMID 34675764, 2021).
metastatic disease (2 papers, 2020 to 2021). "On the other hand, clonal mutations in ARNT (OVA_047), NTRK1 (OVA_048), MYH9 (OVA_047) and PPARG (OVA_047), and subclonal mutations in ITGAV (OVA_047) and PTPRT (OVA_003) were all specific to metastatic tumours." (PMID 32099096, 2020).
non-alcoholic fatty liver disease (2 papers, 2022 to 2024). "Research from Christopher Scott, for example, suggests that increasing ARNT expression may be a potential therapeutic approach in the transition from nonalcoholic fatty liver disease to steatohepatitis." (PMID 35769097, 2022). "In conclusion, this study revealed that MALAT1 could promote hepatic lipogenesis in nonalcoholic fatty liver disease by modulating miR-206/ARNT axis." (PMID 35769097, 2022). "In non-alcoholic fatty liver disease (NAFLD), lncRNA-MALAT1 regulates hepatic lipid accumulation mediated by PPARα/CD36 through the miR-206/ARNT axis, positively correlating with the severity of NAFLD." (PMID 39044218, 2024).
pancreatic cancer (2 papers, 2010 to 2011). "Similarly, embryonic stem cells and pancreatic cancer cells under hypoglycaemia induced HIF target gene expression in a manner dependent on the HIFα dimerisation partner ARNT, but independent of HIF-1α." (PMID 20637078, 2010).
pituitary tumor (2 papers, 2012 to 2016). A benign or malignant neoplasm affecting the pituitary gland. "Consequently, elevated and aberrant cAMP signalling, often seen in pituitary tumors, may imbalance AhR/ARNT and ARNT/Hif-1e signalling." (PMID 23300914, 2012). "The destabilization of AhR would naturally imbalance assembly of AhR/ARNT complex and it has been shown that levels of either ARNT or ARNT2, but not both, are devoid in AIP-deficient mouse pituitary tumors." (PMID 23300914, 2012).
psoriasis (2 papers, 2015 to 2020). An autoimmune condition characterized by red, well-delineated plaques with silvery scales that are usually on the extensor surfaces and scalp. "We found that rs3132089, a promoter variant of the HCP5 gene, is highly linked with psoriasis risk SNP rs3134792 (r2 = 0.9253) and located on the binding motif of ARNT and BHLHE40 proteins, which is predicted to result in decreased binding." (PMID 31969149, 2020).
renal carcinoma (2 papers, 2015 to 2023). A carcinoma arising from the epithelium of the renal parenchyma or the renal pelvis. "This has led to the development of selective HIF-2 inhibitors, which specifically block dimerization of HIF-2α with HIF-1β/ARNT to slow renal cancer progression." (PMID 36725335, 2023). "Interestingly, the results demonstrate that pVHL status affects radiosensitivity and ARNT mRNA and protein expression in both renal carcinoma cell models analysed." (PMID 26572229, 2015).
renal fibrosis (2 papers, 2021). A final common manifestation of a wide variety of chronic kidney diseases characterized by glomerulosclerosis and tubulointerstitial fibrosis. "Low-dose tacrolimus exerts antifibrotic, renoprotective effects in a model of renal fibrosis via ARNT-mediated transcription of bone morphogenetic protein receptor type 1A." (PMID 34424825, 2021). "We next aimed to explore whether observed additive effect of LB100 to FK506/GPI1046-induced ARNT homodimer formation and ALK3 expression also correlated with further attenuation of renal fibrosis." (PMID 34912030, 2021).
Sepsis (2 papers, 2024 to 2025). Sepsis is defined as life-threatening organ dysfunction caused by a dysregulated host response to infection. "TH17 and Treg-associated ARNT are also upregulated in sepsis." (PMID 40699834, 2025). "Focusing on hub genes (putative driver transcription factors), they identified the HIF-1 transcription factor complex (HIF1α and ARNT [HIF1β]), which is involved in immune cell metabolism, coagulation, proliferation, apoptosis, and, ultimately, sepsis survival." (PMID 38991496, 2024).
viral infections (2 papers, 2022 to 2023). "Contrary to its binding partner, HIF-1α, whose role in virus infection has been extensively investigated, the antiviral activity of ARNT has not been well studied." (PMID 35891329, 2022).
acute lymphoblastic leukaemia (1 paper, 2012). "ARNT was examined, since down-regulation of the AHR/ARNT pathway by epigenetic means in acute lymphoblastic leukaemia (ALL) may be extrapolatable to myeloid disease." (PMID 22348345, 2012).
alcoholism (1 paper, 2021). "Further in the line are genes participating in circadian clock function such as ARNT, ARNT2, and PER2 which have been implicated in anxiety disorders–alcohol dependence comorbidity and D-box binding protein gene (Dbp) supposedly influencing the risk for both bipolar disorder and alcoholism." (PMID 34201295, 2021).
asthma (1 paper, 2019). "However, it has recently also been reported that mice lacking ARNT/ HIF-1α signalling in myeloid cells have increased allergic response in both a house dust mite model and an OVA murine asthma model, which may be driven by decreased IL-10 production." (PMID 31800592, 2019).
autoimmune hepatitis (1 paper, 2022). Hepatitis caused by autoantibodies. "Additionally, a previous study also suggests that binding of AhR with Erα exhibits higher affinity compared to ARNT, and alterations of AhR signaling significantly influence the functions of Tregs in autoimmune hepatitis." (PMID 36601108, 2022).
benign meningioma (1 paper, 2023). A grade I, slowly growing meningioma. "The primary cultured cells from benign meningiomas in our study showed responses to the hypoxia mimetic (in terms of mRNA expression of AhR, ARNT, and an AhR target gene) that differ from those described in the literature; this discrepancy may be due to differences between the analyzed tissues." (PMID 37305351, 2023). "Therefore, the hypoxia developing in benign meningioma as a consequence of endovascular embolization may interfere with the AhR signaling pathway at the level of AhR and ARNT mRNA expressions, and this effect does not depend on the histological structure of the meningioma." (PMID 37305351, 2023).
brain tumor (1 paper, 2024). "Notably, the in vivo xenograft mice model revealed that the overexpression of ARNT induced tumor growth and significantly desensitized the brain tumors to TMZ treatment." (PMID 38806469, 2024).
endometritis (1 paper, 2024). An acute or chronic, usually bacterial infectious process affecting the endometrium. "Interestingly, the level of HIF-1A mRNA was strongly increased after LPS treatment and furthermore HIF-1α/ARNT consensus binding motifs were highly enriched in the hypo-methylated DMRs supporting a functional role for these transcription factors in this endometritis model." (PMID 39337320, 2024).
folate deficiency (1 paper, 2012). A nutritional condition produced by a deficiency of FOLIC ACID in the diet. "Precise biological mechanisms of exposure to Dioxin are epigenetic, based on activation of the AhR/ARNT (aryl hydrocarbon receptor/aryl hydrocarbon receptor nuclear translocator) complex of spermatogenesis, leading to folate deficiency as the cause of NTD phenotype." (PMID 22900183, 2012).
glioblastoma (1 paper, 2024). The most malignant astrocytic tumor (WHO grade IV). "Disrupting ARNT/p38α interaction via the ARNT PAS-A domain attenuates chemoresistance in glioblastoma cells." (PMID 38806469, 2024). "Additionally, co-immunoprecipitation in 7209 and U87MG glioblastoma cell lines clearly showed endogenous ARNT interacts with p38α to form a protein complex." (PMID 38806469, 2024). "In this study, we found that ARNT expression is significantly upregulated in glioblastoma multiforme (GBM) and its higher expression correlates with poorer prognosis." (PMID 38806469, 2024). "Although ARNT has been confirmed as an oncogene playing a critical role in various cancers, its functional role in glioblastoma multiforme (GBM) has not been fully elucidated." (PMID 38806469, 2024).
Glucose intolerance (1 paper, 2016). Glucose intolerance (GI) can be defined as dysglycemia that comprises both prediabetes and diabetes. "In adipose tissue, ARNT positively controls genes linked with angiogenesis (Vegf), and thus its deletion prevents adipose expansion and glucose intolerance." (PMID 28005939, 2016). "Selective deletion of ARNT in beta cell of the pancreas leads to glucose intolerance, impaired insulin secretion and deregulated islet gene expression." (PMID 28005939, 2016).
hyperandrogenism (1 paper, 2023). Excessive secretion of androgens from the adrenal glands or gonads. "In women with PCOS, a correlation between elevated levels of AhR, ARNT, CYP1A1, and CYP1B1 genes and clinical hyperandrogenism, follicular fluid testosterone levels, and disturbed folliculogenesis was observed." (PMID 37572199, 2023).
hypertriglyceridemia (1 paper, 2017). A laboratory test result indicating elevated triglyceride concentration in the blood. "Hepatic ARNT may be a novel therapeutic target for improving post-prandial hypertriglyceridemia and glucose homeostasis." (PMID 29190746, 2017).
liver cancer (1 paper, 2024). An epithelial or non-epithelial malignant neoplasm that arises from the liver. "So far, TCDD is known to directly induce Serpine1 through an AhR- and ARNT-dependent mechanism in mouse liver cancer cell lines." (PMID 39596044, 2024).
liver inflammation (1 paper, 2019). "The results of this research show that deletion of ARNT in myeloid cells causes liver inflammation and steatohepatitis after high-fat diet." (PMID 31800592, 2019).
medulloblastoma (1 paper, 2014). A malignant, invasive embryonal neoplasm arising from the cerebellum. "We asked whether increased expression of ARNT and GDI2 was associated with an increased risk of metastasis in medulloblastoma patients." (PMID 25059231, 2014).
meningioma (1 paper, 2023). A generally slow growing tumor attached to the dura mater. "Because the NcoA2 inhibits proteins of the bHLH/PAS family, such as HIF-1α, ARNT, and AhR, it is likely that in the molecular processes of meningioma ischemic hypoxia, AhR signaling probably plays a more important role than the HIF-1α pathway does." (PMID 37305351, 2023). "It has been demonstrated that AhR signaling pathway components such as AhR and ARNT (also known as HIF-1β) were activated as meningioma malignancy progresses from low to high." (PMID 37305351, 2023). "At the same time, mRNA levels of AhR, ARNT, and NcoA2 in the meningiomas subjected to hypoxia as a result of the embolization were statistically significantly lower than those in the nonembolized meningiomas." (PMID 37305351, 2023). "The exposure of the meningioma cell lines to chemically induced hypoxia increased the level of AhR mRNA ninefold as compared with the control cultured cells but did not alter the mRNA level of ARNT and of an AhR target gene (CYP1B1)." (PMID 37305351, 2023). "mRNA expression of HIF-1α, AhR, ARNT, and HIF-1α and AhR target genes did not change when meningioma cells were incubated with B[a]P (AhR agonist)." (PMID 37305351, 2023). "As revealed by our analysis of mRNA expression in samples of meningioma tissue subjected to hypoxic ischemic preconditioning, the expression of HIF-1α and its target genes (VEGF-A, c-Myc, and GLUT1) is not affected by this procedure, whereas AhR, ARNT, and NcoA2 expressions significantly decreases." (PMID 37305351, 2023).
metabolic syndrome (1 paper, 2017). A cluster of metabolic risk factors for CARDIOVASCULAR DISEASES and TYPE 2 DIABETES MELLITUS. "We next assessed the effect of ARNT deletion on serum triglyceride as increased levels are a feature of the metabolic syndrome." (PMID 29190746, 2017).
Ovarian cyst (1 paper, 2024). The presence of one or more cysts of the ovary. "There was a greater expression of AHR mRNA and a lower expression of ARNT mRNA in endometriotic ovarian cysts compared with healthy ovarian tissues." (PMID 38468402, 2024).
preeclampsia (1 paper, 2023). Preeclampsia is a hypertensive disorder of pregnancy that is characterized by new-onset hypertension with proteinuria presenting after 20 weeks of gestation, and depending on mild or severe forms may initially present with severe headache, visual disturbances, and hyperreflexia. "Seven genes (including MKNK1, ARNT, FLT1, SERPINE1, ENO3, LDHA, BCL2) were screen out to build potential diagnostic model of preeclampsia." (PMID 37020283, 2023). "In summary, our study identified MKNK1, ARNT, FLT1, SERPINE1, ENO3, LDHA, BCL2 out of HIF1-signaling pathway as novel diagnostic biomarkers for preeclampsia patients, and a diagnostic signature based on these genes is constructed for preeclampsia." (PMID 37020283, 2023).
Pruritus (1 paper, 2022). Pruritus is an itch or a sensation that makes a person want to scratch. "However, the AHR/ARNT axis appears to be involved in the development of pruritus in AD since the ARNT gene encodes the neurotrophic factor artemin responsible for epidermal hyperinnervation and pruritus." (PMID 36551332, 2022).
pulmonary disorders (1 paper, 2016). "Domain databases also determined shared protein domain with AHR (aryl hydrocarbon receptor) and ARNT (aryl hydrocarbon receptor nuclear translocator), involved in regulation of inflammatory processes implicated in multi-factorial diseases like pulmonary disorders." (PMID 26731791, 2016).
sarcoidosis (1 paper, 2019). Sarcoidosis is a multisystemic disorder of unknown cause characterized by the formation of immune granulomas in involved organs. "Sarcoidosis AMs also show a higher expression of ARNT and p300." (PMID 30946009, 2019). "Here, we show that sarcoidosis AMs and monocytes in normoxic ex vivo culture conditions and without any stimulation exhibit constitutively active HIF-1α and HIF-1β (ARNT) along with its coactivator, p300." (PMID 30946009, 2019).
serous ovarian tumor (1 paper, 2021). "During serous ovarian tumor formation, activated AHR in the cytoplasm could cooperate with SRC, enter cell nuclei, bind to AHR nuclear translocator (ARNT) together with TATA-Box Binding Protein (TBP), and act on DNA to initiate AHR-responsive genes to cause tumor or cancer initiation." (PMID 34440070, 2021).
small cell carcinoma (1 paper, 2023). A neuroendocrine carcinoma composed of small malignant cells which are often said to resemble "oat cells" under the microscope. "The principal studies between ARNT genes suggest a possible relation with small-cell cancer." (PMID 36825998, 2023).